RNU6-792P (RNA, U6 small nuclear 792, pseudogene)
Gene: Small nuclear RNA gene on chromosome 1 (111,490,317 to 111,490,423, reverse strand). Ensembl gene ENSG00000200360.
Homologues: Orthologues: chimpanzee U6 (97% identical), macaque U6 (97% identical), mouse Gm24388 (84% identical), pig U6 (83% identical), guinea pig U6 (79% identical), rat U6 (79% identical), pig U6 (77% identical), mouse Gm25482 (76% identical), rabbit U6 (76% identical), dog U6 (75% identical). Paralogues in human: RNU6-1303P (89% identical), RNU6-166P (89% identical), RNU6-41P (89% identical), RNU6-820P (89% identical), RNU6-1024P (88% identical), RNU6-1060P (88% identical), RNU6-1152P (88% identical), RNU6-15P (88% identical), RNU6-19P (88% identical), RNU6-259P (88% identical), RNU6-35P (88% identical), RNU6-45P (88% identical), and 1286 more.